IL13 (interleukin 13)
Diseases named in the same sentence as IL13 in open-access papers (continued):
Sharing a sentence is not in itself a finding about the gene and the disease.
allergic rhinitis (continued). "Application of A. cepa on the nasal cavity of BALB/c mice with allergic rhinitis revealed remarkable decreases in IgE and inflammatory cytokines IL-4, IL-5, IL-10, and IL-13." (PMID 34552650, 2021). "The emerging innovative drugs include mAbs targeting on characteristic pathways of type 2 inflammation, such as those of IgE, the IL-5, and IL-4/IL-13 which are involved in several pathologic condictions including CRSwNP or allergic rhinitis." (PMID 35387050, 2021). "Yue and colleagues found that linc00632 was down-regulated in nasal tissues of allergic rhinitis patients and inhibited IL-13 induced inflammatory cytokine and mucus production." (PMID 32637070, 2020). "Ginsenoside Rd suppressed ovalbumin-induced expression of IgE, IL-4, IL-5, and IL-13 in nasal mucosa and bronchoalveolar lavage fluid and alleviated gut dysbiosis in mice, resulting in the attenuation of allergic rhinitis." (PMID 32326081, 2020). "It has been reported that an increase in IL-31 levels was detected in patients with allergic rhinitis and IL-31 induced production of IL-4, IL-5 and IL-13 in PBMC and nasal epithelial cells from patients with allergic rhinitis." (PMID 30647024, 2019). "Patients presenting with nasal allergies and Th2-predominant upper airway allergic rhinitis had higher IL-13 expression correlated with low BPIFA1 expression and high sinusitis infection rate than patients lacking a background with allergic rhinitis." (PMID 30255091, 2018). "For example, reduction of IL13Rα1 expression by miR-143 has been shown to reduce IL-13-induced mucus production in nasal epithelial cells from patients with allergic rhinitis." (PMID 29438285, 2018). "ILC2, a type of innate lymphoid cells producing cytokines such as IL9, and IL13, plays an important role in eosinophilic asthma in response to respiratory infections, and is over-expressed in eczema lesions and in allergic rhinitis subjects." (PMID 28598986, 2017). "In this preliminary study, Ph-positive patients with allergic rhinitis who received acupoint herbal plaster treatments manifested gene expression changes involved in the “Immune response_IL-13 signaling via JAK-STAT” pathway." (PMID 27814709, 2016). "In allergic rhinitis, IL-13 is expressed in the nasal mucosa of patients with perennial allergic rhinitis and after allergen provocation." (PMID 22853438, 2012). "To further elucidate the potential role of IL-31 in allergic rhinitis, we studied the release of IL-31 and IL-13 into nasal secretions and serum after unilateral allergen challenge in seasonal allergic volunteers." (PMID 22853438, 2012). "In the present study we studied the release of IL-31 and IL-13 in allergen-challenged allergic rhinitis patients." (PMID 22853438, 2012). "In a mouse model of allergic rhinitis, an essential contribution of IL-13 to the late-phase response in allergic rhinitis was shown by means of either IL-13−/− (knockout) mice or a soluble IL-13 inhibitor." (PMID 22853438, 2012). "In nasal secretions of patients with seasonal allergic rhinitis, IL-13 appeared between 4 and 8 h and peaked 6 h after nasal allergen challenge." (PMID 22853438, 2012). "Our results confirm previous findings describing an involvement of IL-13 in nasal late-phase response in allergic rhinitis." (PMID 22853438, 2012). "Upon activation, ILC2s release IL-5 and IL-13, promoting eosinophilic inflammation, goblet cell hyperplasia, mucus hypersecretion, and tissue remodeling, all central features of chronic rhinosinusitis with nasal polyps (CRSwNP) and severe allergic rhinitis." (PMID 41752128, 2026). "Maternal allergic history may reflect a heritable predisposition to atopy, with several studies identifying polymorphisms in immune-related genes such as IL-4, IL-13, and the filaggrin gene (FLG) that are linked to an increased risk of allergic rhinitis." (PMID 40422270, 2025).
allergic rhinitis (continued). "In addition, miR-15a-5p has been proven to be involved in allergic rhinitis immune response by inhibiting IL-13-induced expression of GM-CSF, eotaxin and MUC5AC nasal epithelial cells." (PMID 40076712, 2025). "When looking into the literature, a decrease in IL-4, IL-5 and IL-13 after acupuncture could be seen in animal experiments, namely in rats suffering from allergic rhinitis." (PMID 35301577, 2022). "The IL-4/IL-13 axis is involved in the pathogenesis of allergic rhinitis (AR)." (PMID 35372516, 2022). "Furthermore, allergen-induced IL-31 protein production by PBMCs in patients with allergic rhinitis was significantly and positively correlated with the production of IL-13." (PMID 22853438, 2012). "Furthermore, we confirmed previous reports about the increase of IL-13 in nasal secretions particularly in the late-phase response in allergic rhinitis." (PMID 22853438, 2012). "While GM-CSF shows its presence in urticaria as well as allergic rhinitis along with IL-13." (PMID 20616938, 2010). "However, IL-4, IL-5 and IL-13 levels may be elevated in the nasal secretion of patients with persistent severe allergic rhinitis." (PMID 30846420, 2020). "Because GSEA revealed that the genes upregulated in nasal brushing samples from mite allergic patients and the genes induced by IL-4 and IL-13 were significantly enriched in our dataset, our data support the notion that pathways underlying allergic rhinitis are common regardless of the allergen." (PMID 23950865, 2013). "However, a recent meta-analysis using data from these 6 studies has shown that the A allele of IL13 SNP rs20541 was associated with an increased risk of allergic rhinitis, whereas no such relationship existed between IL13 SNP rs1800925 and allergic rhinitis." (PMID 22023794, 2011). "Treatment of rat models of allergic rhinitis after particulate matter (PM2.5) exposure with RosA (20 mg/kg, i.p.)for 7 days remarkably reduced the levels of IL‐4 and IL‐13, while enhancing IFN‐γ levels in nasal lavage fluid." (PMID 41523289, 2026). "According to the literature, in experimental mice with allergic rhinitis treated with berberine, serum IgE, GATA-3, IL-4, and IL-13 mRNA levels, as well as tissue eosinophil numbers, were significantly reduced." (PMID 41001345, 2025). "Studies showed to exposure to PM2.5 worsened symptoms in rats with allergic rhinitis, leading downregulated of IFN-γ and upregulated of IL-4, IL-13, and eosinophils in nasal fluid." (PMID 38961398, 2024). "IL-13, a TH2-skewed cytokine, is produced in allergic rhinitis and CRSwNP of an eosinophilic-predominant type." (PMID 26646664, 2015). "Compared to allergic rhinitis mice, CCR3mAb2 and CCR3mAb3 groups had increased trends in Th1 cytokines (IL-2 and IFN-γ), with statistical significance; and decreased trends in Th2 cytokines (IL-4, IL-5, and IL-13)." (PMID 38212473, 2024). "Firstly, a mouse model of allergic rhinitis was produced by OVA sensitization followed by an OVA challenge, which resulted in nasal symptoms (nose rubbing and sneezing) and increases in IgE/OVA-IgE, as well as IL-4/IL-13 levels in the nasal fluid." (PMID 32899766, 2020). "IL-4, IL-5, and IL-13 are produced by TH2 type cells and have cardinal roles in allergic rhinitis." (PMID 31807241, 2019). "Allergic rhinitis and chronic rhinosinusitis with polyposis are examples of persistent inflammatory diseases of the upper airway dominated by CD4+ Th2 effector cells secreting IL-4, IL-5, and IL-13 in response to commonly inhaled antigens." (PMID 25090641, 2014). "IL-13 was significantly increased in allergic rhinitis (252.67 fold, P = 0.0001) but not in mev mice." (PMID 22509389, 2012). "One study has revealed increased expression of the IL-13 gene in the epithelial compartment of the nasal mucosa of patients with perennial allergic rhinitis, and no such increase in the nasal epithelial compartment of control subjects." (PMID 22023794, 2011).
allergic rhinitis (continued). "In the other 5 previously cited studies that have investigated IL13 SNPs and allergic rhinitis, gene-environment interactions were not examined." (PMID 22023794, 2011).
Obesity (86 papers, 2010 to 2025). Accumulation of substantial excess body fat. "In general, obesity is associated with elevated levels of cytokines originating from both Th2 and Th1 immune responses, including interleukin (IL)-5, IL-10, IL-12, IL-13, Interferon-gamma (IFN-γ), and tumor necrosis factor alpha (TNF-α)." (PMID 41007770, 2025). "For example, the alternative activation of AT macrophages in obesity has been reported to be inextricably linked with eosinophils by an IL-4- or IL-13-dependent process." (PMID 37720534, 2023). "Obesity was associated with increased levels of both pro-inflammatory (IL-13) and anti-inflammatory (IL-1RA) cytokines." (PMID 36769452, 2023). "The studies report that obesity is associated with significantly elevated levels of Il-5, Il-10, Il-12, Il-13, IFN-γ and TNF-α." (PMID 34444287, 2021). "Early during infection (i.e., d3 p.i.), obesity was again associated with reduced production of cytokines IL-13, IL-5, IL-12p70, IFNγ, TNFα, IL6, and IL-1β, as well as IL-28b (IFNλ), IL-17, and IL-15." (PMID 26110868, 2015). "A few studies have shown that obesity exerts IL-4/IL-13-associated inflammatory responses." (PMID 39564133, 2024). "Obesity-associated inflammation in adipose tissue, for example, can be normalized by IL-13." (PMID 37629063, 2023). "Obesity-associated inflammation in adipose tissue and the associated release of inflammatory cytokines can be normalized, for example, by the administration of IL-13." (PMID 37629063, 2023). "We aimed to address this gap by determining IL-33 serum level and its downstream type 2 inflammatory cytokines interleukin-5 (IL-5) and interleukin-13 (IL-13) in overweight/obese population, and analyzing the specific associations between IL-33 and obesity metabolic phenotypes." (PMID 33541367, 2021). "Whereas, IL-13 was proved to be associated with obesity-related colorectal tumorigenesis." (PMID 32283835, 2020). "Nonetheless, contradicting the implied protective role, animal studies have implicated IL-13 in the development of metaplasia during gastric carcinogenesis and obesity-related CRC while our own results have shown systemic interleukin to be elevated in both CRC and high-risk conditions." (PMID 32512917, 2020). "As IL-4 and IL-13 have an anti-inflammatory effect in the fat metabolism, and treatment with dupilumab blocks IL-4 and IL-13, this might interfere with activation of brown fat and thus increase the risk for obesity in patients with AD." (PMID 32962676, 2020). "The presence of higher values of IL4 and IL13 in obese patients may suggest that obesity is associated with a more anti-inflammatory cytokine expression during critical illness." (PMID 26064774, 2015). "Interestingly, BM upregulated specific Th2 cytokines IL-5, IL-10 and IL-13, which have been demonstrated to protect obesity-associated inflammation." (PMID 21639917, 2011). "Given the increased incidence of metabolic disorders resulting from the genetic ablation of Th2 or M2 inducers (e.g., Il4, Il13, Il33, Stat6, or Pparg), the decreased whole-body Th2/M2 status resulting from Pla2g5 deficiency may also contribute to the exacerbation of obesity-associated inflammation." (PMID 29259680, 2016). "Several clinical studies highlight increased body mass index as a protective factor through the immunomodulatory effect of obesity secondary to increased serum levels of interleukins with an anti-inflammatory role (IL-4, IL-13)." (PMID 40002559, 2025). "Although IL-4 and IL-13 share receptor components and overlapping signaling pathways, their roles in obesity-related adipose tissue fibrosis are still unclear." (PMID 41007770, 2025). "Th2 cytokines, such as IL-4, IL-5, and IL-13, regulate energy metabolism, insulin resistance, and obesity-related issues." (PMID 41007770, 2025). "The available evidence is limited, particularly for IL-13, which is scarce in the context of obesity." (PMID 41007770, 2025).
Obesity (continued). "This review aims to clarify the role of IL-4, IL-5, and IL-13 in contributing to the immunometabolic changes observed in obesity." (PMID 41007770, 2025). "They observed increased levels of IL-5, IL-13, and CC chemokine receptor type 3 with obesity, the latter involved with eosinophil chemotaxis." (PMID 39427706, 2025). "Obesity-influenced estrogen would enhance Th2 response, and increase the production of IL-4 and IL-13; estrogen also reduces response to inhaled corticosteroid." (PMID 41250031, 2025). "Like mast cells, eosinophils protect against obesity by regulating thermogenesis through the actions of IL-4 and IL-13." (PMID 41007770, 2025). "First, the increase in IL-13 has been observed in certain contexts, such as obesity or chronic inflammation, probably due to a combination of increased activity of ILC2s and Th2 cells within inflamed adipose tissue." (PMID 39273478, 2024). "Having demonstrated the role of obesity in modulating the subsequent type 2 inflammation, we next determined if PA promotes pre-existing type 2 inflammation induced by IL-13 or HDM." (PMID 37287831, 2023). "The hydrodynamic injection of the IL-13 gene was able to completely prevent Western-diet-induced obesity in the experiments conducted here." (PMID 37629063, 2023). "In adipose tissue, ILC2s induce the type 2 cytokines IL-5 or IL-13 and increase eosinophils numbers, and M2 macrophages stimulate inflammation, which promotes immunity and metabolic homeostasis and curbs obesity." (PMID 38283340, 2023). "Collectively, these data suggested that IL-13 suppressed gluconeogenesis in the HFD-fed obesity model." (PMID 36109558, 2022). "Nonetheless, obesity‐related dose of leptin elevated not only the release of IL‐6 and IL‐17, but also IL‐5 and IL‐13 by CD4+ T cells in lean‐derived cell cultures from patients." (PMID 35734271, 2022). "From this point of view, previous studies demonstrated that circulating levels of IL-13 are reduced in diabetic patients that exhibit increased insulin resistance and IL-13 overexpression protects against high-fat-diet-induced obesity." (PMID 33526854, 2021). "We found a regulation of IL-6, IL-8, IL-15, IL-18, and FGF21 in plasma by exercise, while obesity status increased IL-13 and decreased IL-8 and SPARC in the circulation." (PMID 32132925, 2020). "This phenotype was further exaggerated in the context of obesity, where cholangitis induced in NLRP3-deficient obese mice resulted in further exacerbated histopathology and increased levels of IL-13 and TNFα, suggesting a diet-specific profile." (PMID 32716024, 2020). "The helminth-induced immune responses mainly stem from the Th2 mediated cytokines IL-4, IL-10 and IL-13, the functions of which in nutrient metabolism and obesity are not fully understood and are an area of active research." (PMID 29545532, 2018). "In our study, serum concentrations of IL-13 exhibited a strong correlation with obesity-related anthropometrical parameters including BMI and central obesity." (PMID 29675435, 2018). "A similar reduction is observed after anti-IL-13 in obese mice, suggesting that IL-33-dependent increases in IL-13 contributed to obesity-related increases in effects of O3 on baseline pulmonary mechanics (PBS values)." (PMID 27472835, 2017). "The findings demonstrate that a transient early postnatal overweight induces early-onset (P21) obesity, accompanied by activation of pulmonary adipocytokine/insulin signaling and increased pulmonary expression of pro-asthmatic IL-6, IL-13, IL-17A and Tnf-α." (PMID 27087690, 2016). "IL-4 and IL-13 are able to generate a M2-state and disrupting M2 activation leads to obesity and IR." (PMID 25781614, 2015). "In participants with general obesity, levels of IL-4, IL-10 and IL-13 were significantly elevated in participants with low physical activity, even when controlled for BMI which was negatively associated with physical acitivity." (PMID 25781614, 2015).
Obesity (continued). "These clusters included previously reported biomarkers for obesity-related disease and potential new biomarkers such as IL-3 and IL-13." (PMID 21203453, 2010). "The intestinal nematode H. polygyrus could protect against obesity by triggering the production of Th2-mediated cytokines, such as IL-4, lL-10 and IL-13, and enhancing the anti-inflammatory M2 macrophages levels." (PMID 40708918, 2025). "However, in obesity, IL-4 and IL-13 have been found to have significant metabolic effects that are not yet fully understood." (PMID 41007770, 2025). "For example, obesity, inflammaging, cardiovascular disease, hypertension, and rheumatoid arthritis are characterized by elevated concentrations of circulating cytokines, such as IL-1b, IL-6, IL-8, IL-10, IL-13, TNF-α, and IFN-γ." (PMID 39408907, 2024). "Thus, a connection between obesity-induced inflammation, the anti-inflammatory IL-13, and colorectal carcinogenesis was established." (PMID 37629063, 2023). "In addition to these cells, ILC2s (produce proinflammatory IL-5 and IL-13) from the small intestine, have been also shown to be involved in the diet-induced obesity." (PMID 37720534, 2023). "Our data suggests that obesity may enhance IL-13-mediated airway type 2 inflammation as well as neutrophilic inflammation." (PMID 37287831, 2023). "Research indicates that obesity significantly induces the production of pro-inflammatory adipokines, while adipose tissue secretes corresponding anti-inflammatory cytokines (such as IL-4, IL-10, IL-13, IL-19)." (PMID 38138996, 2023). "The increased levels of IL-10 and IL-13 and decreased levels of IL-5 might be involved in maintaining immune tolerance during the initial stage of obesity, but later, might indirectly support M1 macrophage function to maintain chronic inflammation." (PMID 35456006, 2022). "Previous studies have shown that expression of IL-10 and IL-13 in WAT cells may be elevated by obesity-induced ER stress." (PMID 33717200, 2021). "As the IL-4Rα is a shared receptor for IL-4 and IL-13, altered IL-13 levels in obesity might also play a role." (PMID 34302121, 2021). "The decrease in the concentration of Th2 cells observed in obesity results in a decrease in the concentration of anti-inflammatory cytokines, such as interleukin 4 (IL-4), interleukin 5 (IL-5), interleukin 10 (IL-10) and interleukin 13 (IL-13)." (PMID 34564433, 2021). "Further investigations would be required to assess how obesity and/or T2D affect circulating IL-13." (PMID 32132925, 2020). "Inflammation provoked by obesity notably increased expression of IL-13, which in turn leads to increased expression of IL-13R1, ending up with activation of downstream phosphorylation of the transcription factor STAT6, suggesting a possible mechanism of carcinogenesis in colon cancer." (PMID 32283835, 2020). "In this regard, an increase expression of the cytokine IL-13, contributing to AT inflammation, has been reported to play an important role in obesity-related colon carcinogenesis, while IL-37 signaling has been described to play an inhibitory role in innate immune responses." (PMID 32714872, 2020). "Thus, IL-33 had a protective effect against obesity, insulin resistance and diabetes in animal models due to the reduction of resistin expression, accumulation of Th2 cells and IL-5, IL-13 and the suppression of T effectors cells by IL-10 releasing." (PMID 32824505, 2020). "Inflammatory cytokines appear to play a key role in linking obesity and colorectal carcinogenesis particularly so for IL-6 and tumor necrosis factor-α; a recent study also describing IL-13 as a potential factor involved in the development of obesity-related colon cancer onset." (PMID 31906216, 2019). "However, we only studied the relationship of obesity-related anthropometrical parameters with IL-13 serum concentrations by means of statistical correlation models and the discussion of these results makes no attempt to conjecture beyond that." (PMID 29675435, 2018).